ID1 (inhibitor of DNA binding 1)
Diseases named in the same sentence as ID1 in open-access papers (continued):
Sharing a sentence is not in itself a finding about the gene and the disease.
cancer (continued). "In addition, genes whose expression was suppressed by BA included ID1, which is associated with regulation of CSCs and treatment resistance; SRSF1, which contributes to RNA splicing that alters cancer stem cell plasticity; and LIN28B, an oncogenic stem cell factor involved in EMT." (PMID 40316727, 2025). "Interestingly, a potential role of ID1 in the regulation of cancer stemness has been demonstrated." (PMID 37759448, 2023). "Consequently, we hypothesize that Orai3 contributes to cancer stemness through the elevation of ID1 expression." (PMID 37759448, 2023). "Finally, scRNA sequencing of HCC patients and investigation of clinical specimens also verified that the expression of ID1 is correlated with aberrant differentiation of HPCs into cancer stem cells, patients with high levels of ID1 in HPCs showed a poorer prognosis." (PMID 37085918, 2023). "The association of ID1 in purified PDAC cancer cells has never been described." (PMID 35941362, 2022). "However ten years later, another study determined that overexpression of ID1 was found to be closely correlated with that of VEGF, an endothelial growth factor that has a central role in cancer angiogenesis, and to be associated with high microvessel density and patient survival in PDAC16." (PMID 35941362, 2022). "Thus, we hypothesize that the synergy of ID1 and NK-κB may promote the generation of cancer stem-like cells in keratinocytes." (PMID 33442406, 2021). "In addition, ID1 was shown to keep cancer stemness with epithelial traits." (PMID 34869246, 2021). "Hence, the hyperuricemia may potentiate invasiveness and metastasis in cancer cells by increasing the ID1 and COX-2 expression via XOR downregulation." (PMID 34588926, 2021). "However, besides cancer types, the controversial conclusion may also related to the concrete expression amount of Id1, the duration of treatment, the observation time and specific medicine." (PMID 32410828, 2020). "ID1-expressing cells within the drug resistant cancer cell pool might have preferentially proliferated following transplantation into the mouse host, while the ID1-expressing cells within the untreated cancer cell pool might have had a decreased proliferation potential." (PMID 31013771, 2019). "Id-1 has been shown to promote cell survival by activating NF-κB signaling pathway and it has been suggested that it may be one of the upstream regulators of NF-κB in various cancer." (PMID 29233161, 2017). "Furthermore, Id-1 has been reported to promote survival and metastatic ability of cancer cells." (PMID 29233161, 2017). "Furthermore, unlike Id1 that promotes cell proliferation, its isoform causes a cancer stem cell-like phenotype and promotes its self-renewal." (PMID 28122577, 2017). "Furthermore, our findings provide additional evidence that Id1 may be used to assess or grade the severity of pathologic inflammatory conditions, as has been done previously for some cancers." (PMID 27071670, 2016). "ID1 and ID3, associated with cell differentiation, angiogenesis and reported to be increased in several cancers; MAPK8 associated with cell cycle control and cell differentiation and CDC6 a protein involved in DNA replication and which has been implicated in EMT and cancer development." (PMID 25207642, 2014). "Increased expression of ID1 in the OS biopsies has been shown to be involved in the proliferation, survival, angiogenesis, metastasis, and formation of a permissive metastatic niche in other cancer types, and may be similarly involved in OS." (PMID 20551950, 2010). "Therefore, ID-1 protein may be an important new target molecule for antiangiogenic drug design in cancer treatment." (PMID 19002177, 2008). "However, the clinicopathological and biological significance of Id-1 overexpression remains unclear in human primary cancer." (PMID 15026801, 2004).
cancer (continued). "The other possible explanation is that Id-1 expression is tissue specific and has a different role in the development of various tissues that may contribute to different roles in carcinogenesis and in different biologic behaviours of different human cancers." (PMID 15026801, 2004). "Most notably, many of these early response alterations in the cancer cells are known pro‐angiogenic transcripts, including ITGA2, CLDN12, SMAD7, MET, KLF4, ID3 and ID1." (PMID 40116596, 2025). "This role for ID1 in promoting VM was supported by ID1 genetic knockdown or chemical inhibition interrupting VM formation by MDA‐MB‐231‐LM2 (breast) and BxPC‐3 (pancreatic) cancer cells." (PMID 40116596, 2025). "Further support for ID1 in VM formation includes the modulation of PDGF, a known regulator of VEGF expression in cancer and a modulator of cellular transformation." (PMID 40116596, 2025). "In a similar manner to the PAF1 knockdown, CDC73 or CTR9 knockdown inhibited cell proliferation, reduced the expression levels of most cancer stem cell marker genes including LGR5 and ID1, and increased those of KRT20 and MUCs." (PMID 38182897, 2024). "ID1 and ID3 genes have been identified as predictors of poor response in Colombian adult B-ALL patients, contributing to cancer development." (PMID 39676870, 2024). "Concurrent knockout of ID1 and ID3 enhances the sensitivity of cancer stem cells to the chemotherapy drug oxaliplatin." (PMID 38195969, 2024). "Crucially, expression of UBE2A mutants reduced the expression levels of most cancer stem cell marker genes including those of LGR5 and ID1 and increased those of KRT20 and MUCs." (PMID 38182897, 2024). "The dysregulation of significant cancer-related genes (FAM83H, CXCL12, PITPNA, HMOX1, DGKZ, NR5A2, VMP1, and ID1) was confirmed by qRT-PCR." (PMID 36232920, 2022). "Conversely, the mesenchymal markers fibronectin, N‐cadherin and vimentin, the EMT‐TFs Snail, Slug, Zeb1 and Zeb2, and the cancer stem cell markers CD44, Sox2 and Id1 were strongly induced by TGFβ and repressed by BMP in 3D cultures." (PMID 35348275, 2022). "More interestingly, Id1 gene was also found to be remarkably upregulated in Cluster 2, suggesting that Id1 was a consistent marker for PDAC progression and malignant cancer cells in mouse models." (PMID 35941362, 2022). "ID1 and ID2 overexpression has been shown to correlate with enhanced malignant potential in various types of cancers including AML." (PMID 36443709, 2022). "Mechanistically, we identified the Inhibitor of DNA binding 1 and 3 (ID1, ID3), drivers of cancer stemness and plasticity, as previously uncharacterized targets of transcriptional repression by ZNF148." (PMID 36207293, 2022). "Even in the cancer tissues from NSCLS patients, Id1 seems to be significantly related to the vimentin and other EMT-related proteins." (PMID 33936204, 2021). "Inhibitor of DNA binding 1 (ID1) is an oncogenic protein, promoting cancer survival, proliferation, angiogenesis, and metastasis." (PMID 34820369, 2021). "We found all expression-validated cancer and migration-related genes had at least one putative DRE(s) in their promoters, especially CYP1B1, ID1, and SDC1, which had 8, 5, and 6 putative DRE sites, respectively." (PMID 34955744, 2021). "ID1, ID2 and RUNX2 were also shown to conduce to cancer cell invasiveness, and BAMBI is a BMP target gene implicated in CRC metastasis." (PMID 32326239, 2020). "Consistently for both ID1-ID2a and DBL1-ID1a, the highest recovery of cancer cells was observed when using 2.5–10 ng rVAR2-SpyC per μg beads." (PMID 32244341, 2020). "Our finding that EMT depends on TGF-β-induced ID1 expression has implications for the role of SMAD1/5 and the IDs in cancer." (PMID 29376829, 2018). "Taken together, the results provided the first evidence showing that Id1-induced IGF2 from cancer cells can activate stromal fibroblasts in a paracrine manner, and stimulate them to produce VEGF as well as to adopt a more cancer-promoting phenotype." (PMID 28186102, 2017).
cancer (continued). "In this study, we observed that increased stem cell population and activity by Id1 overexpression were reversed by inhibition of Wnt/TCF/c-Myc pathway in both breast normal and cancer cells." (PMID 25938540, 2015). "Inhibitor of Differentiation (ID1), an important helix-loop-helix (HLH) transcription factor involved in the proliferation and progression of many cancer types, was selected for this purpose." (PMID 26649169, 2015). "In our previous study, we demonstrated that Id1 is involved in the upregulation of the PI3K/Akt and survivin pathways which promote the survival of cancer cells." (PMID 24572994, 2014). "Therefore, ID1 overexpression may induce invasion in several cancer types." (PMID 24137437, 2013). "In contrast to Id1, successful knockdown of Id2 in ACCM cells did not lead to a significant decrease in the proliferation rate or invasion of the cancer cells." (PMID 23517130, 2013). "It is reported that ID1 can be induced by BMPs in TGF-β signaling and in turn promotes cancer cell migration." (PMID 21998723, 2011). "Id1 is one of the transcription factors regulated by BMP signaling and its abnormal expression is observed in human cancers." (PMID 20950440, 2010). "Several studies reported that the E-cadherin/catenin complex and P-cadherin, of the cell-cell adhesion family, as well as fascin, Id-1, IGF-R1, and EGF-R genes are important regulators in the progression of several human carcinomas including cervical." (PMID 20862378, 2010). "Of the novel Notch target genes so far analysed at the mRNA level, we chose to focus on VEGF, ID1, and GIMAP5 because of their known involvement in cancer or T cell development." (PMID 19508709, 2009). "Moreover, Id1Lyz-KO in TAMs abrogated the effects of ML323 treatment on cancer stemness and CD8+ T cell migration, indicating the effect of ML323 on TAMs are mediated by Id1." (PMID 37996458, 2023). "Mechanistically, ID1 interacts with STAT1 to induce its cytoplasmic distribution and inhibits STAT1-mediated SerpinB2 and CCL4 transcription, two secretory factors responsible for cancer stemness inhibition and CD8+ T cell recruitment." (PMID 37996458, 2023). "In addition to the downstream effectors of YAP, ID1 and c-MYC have been defined as the markers of BCSCs because ID1( +) cells are enriched for self-renewal in tumorsphere and c-MYC drives a stem-like phenotype in cancer." (PMID 38102651, 2023). "In addition, adding EIF2A protein to the HS-766T cells significantly induced the elevation of ID1 in HS-766T cells, further validating that ID1 gene was regulated by EIF2 signaling in PDAC cancer cells." (PMID 35941362, 2022). "In contrast, in other cancer types such as hepatic or thyroid tumors, the role of ID1 is not so evident." (PMID 33514024, 2021). "In TNBC and other cancers, the ID oncogenic transcripts foster diverse cancer-related events, including EMT, signaling (e.g., EGFR/TGF-beta, K-Ras, WNT, STAT3, PI3K/Akt, OCT-4/ID1/NF-kappaB), where ID genes are a target of many anticancer drugs, including vinblastine." (PMID 34299315, 2021). "We examined the effects of cigarette smoke condensate (CSC) on the formation of cancer stem-like cells, which are rich in octamer-binding transcription factor (OCT)-4, inhibitor of differentiation 1 (ID1), nuclear factor (NF)-κB, and B lymphoma Mo-MLV insertion region 1 homolog (BMI-1)." (PMID 33442406, 2021). "Id1/Id3 do have bona fide functional CCAAT in promoters, bound in cancer cells as per ENCODE data (M. Ronzio, A.B., D.D., R.M., in preparation) and in NTera2 cells: Id1, but not Id3, is bound in vivo by NF-Y in C2C12, parental cells and edited clones." (PMID 32214056, 2020). "This dual effect in both culture conditions suggests that ID1 and ID3 inhibition may be effective on both the attached growth in primary tumors, as well as on the detached growth of disseminated cancer cells." (PMID 32661241, 2020).
cancer (continued). "Other mutational signatures including SBS40, SBS5, ID9, ID1 and ID2 were not significantly enriched more in BRCA1/2-mutated cancers expressing wild-type POLQ than in other types of cancers." (PMID 32885167, 2020). "Furthermore, the important role of ID1 in CSC phenotypes and its participation in the TGF-β-SMAD2/3-ID1 axis make it a candidate for the study of cancer stem cell properties in ESCC." (PMID 31296250, 2019). "Id1 is a member of HLH family which functions as a differentiation inhibitor, and it is overexpressed in many cancers and facilitates the growth and metastasis of cancer." (PMID 30949224, 2019). "Consistent with the known concept that senescent cells can contribute to the growth of non-senescent cancer cells, the tumors in mice with ID1(−)-induced senescence grew faster than controls for about 1 week." (PMID 30154433, 2018). "Finally, we observed that basal expression of CSC-related genes (ID1, CD44, HES7 and TCF3) significantly correlate with ONC201 efficacy in >1000 cancer cell lines and combining the expression of multiple genes leads to a stronger overall prediction." (PMID 28767654, 2017). "Moreover, Gumireddy and colleagues found that ID1 interacted with transcription factor AP-2α (TFAP2A) to suppress S100A9 expression, leading to migratory and invasive phenotypes of cancer cells." (PMID 26662959, 2016). "Studies of knockout mice lacking expression of Id1 have shown its involvement in vasculogenesis and neuroblast differentiation in various cancer models normally characterized by extensive vascularization." (PMID 27071670, 2016). "The distinct role of Id1 reported in this study may arise from the phenomenon of Id1 dependence of NSCLC cells for survival, which renders the cancer cells additionally susceptive to the adjuvant chemotherapy with paclitaxel and cisplatin." (PMID 25344919, 2014). "There have been many studies showing a relationship between Id-1 and EGFR in many types of cancer." (PMID 19014499, 2008). "Our observation of elevated ID1 in TNBC metastases in vivo, together with gene ontology profiling for transcriptional regulation of a vascular‐like phenotype by the cancer cells, provides the strongest evidence to date that ID1 is a higher‐order regulator of VM by cancer cells." (PMID 40116596, 2025). "Here, we found that ML323 administration eliminates cancer stem cells increases CD8+ T cells infiltration simultaneously, and enhances the therapeutic efficacy of anti-CTLA4 antibody or 5-FU, demonstrating the great potential of ID1 as a dual-functional target." (PMID 37996458, 2023). "More importantly, ID1/G6PD signaling was found to be a predictor of unfavourable clinical prognosis in HCC patients, suggesting that the ID1 signaling pathway may be a potential therapeutic target for inhibiting HCC progression and anti-cancer drug resistance." (PMID 29169374, 2017). "Besides, treatment of Id1-overexpressing NSCLC cells with paclitaxel and cisplatin led to a reduced level of phosphorylated Akt at Ser473, which was known a downstream signaling molecule of Id1 in NSCLC and other cancer cells." (PMID 25344919, 2014). "In addition to inducing cell proliferation, Id1 may also induce EMT, inhibit apoptosis and promote migration, invasion, metastasis and drug resistance in several types of cancer." (PMID 24970809, 2014). "As the survival of metastasized cancer cells is dependent on the expression of ID genes, KLF17 may need to remain downregulated as well in order to maintain the released repression of ID1." (PMID 24429391, 2014). "Furthermore, it has been shown that ectopically overexpressed Id1 is able to suppress PARP cleavage in response to different anticancer drugs, which leads to increased apoptosis rates and increased cleaved PARP in different cancer cell lines." (PMID 20842131, 2010).
cancer (continued). "Also, the activated EMT features were also identified in the PDAC cancer cells, as shown by reduced epithelial marker genes expression and upregulated mesenchymal and EMT marker gene expression, suggesting a potential role of ID1 in EMT of PDAC cancer cells in human." (PMID 35941362, 2022). "Knowing that ID1 regulated self-renewal of both normal and cancer stem cells via Wnt/β-catenin dependent c-MYC transcription activation, and ID1 promoted c-MYC expression through MAPK/ERK signal pathway in HCC, we next explored whether ID1 enhanced c-MYC activities through these two pathways." (PMID 29169374, 2017). "Although this study suggests that the scattered hypoxic regions in ID1-overexpressing tumors could potentially contribute to AAT resistance, the characteristics of these regions that may confer resistance to cancer cells are not yet comprehensively understood." (PMID 38658527, 2024). "ID1 and ID3 are expressed only in embryonic and cancer cells, but not in most adult tissues." (PMID 34295890, 2021). "In addition, we found that the BMP targets, ID1 and ID2, were significantly downregulated in the carcinomas, whereas GREM1 and NOG expression increased, albeit not significantly in the case of GREM1." (PMID 27492255, 2016).